PCDHB10 (protocadherin beta 10)
Description:
Potential calcium-dependent cell-adhesion protein. May be involved in the establishment and maintenance of specific neuronal connections in the brain.
Synonyms: PCDH-BETA10; PCHB10
Tractability: Antibody: UniProt places it where antibodies can reach, with medium confidence; UniProt predicts a signal peptide or a membrane-spanning region; its Gene Ontology location is reachable by antibodies, with medium confidence. PROTAC: ubiquitination databases record sites on it.
Gene: Protein-coding gene on chromosome 5 (141,192,353 to 141,195,647, forward strand). Ensembl gene ENSG00000120324.
Subcellular location: Cell membrane
Gene Ontology:
Molecular function: cell adhesion molecule binding; calcium ion binding
Biological process: calcium-dependent cell-cell adhesion; cell adhesion; chemical synaptic transmission; synapse assembly; homophilic cell-cell adhesion; nervous system development
Cellular component: membrane; plasma membrane; synapse
Genetic constraint (gnomAD): Loss-of-function variants: 1 observed, 0.44 expected, observed/expected ratio (o/e) 2.28. That is too few expected variants to judge how well the gene tolerates losing a copy. Missense variants: 1,044 observed, 963.98 expected, observed/expected ratio (o/e) 1.08, 90% interval 1.03 to 1.14. Synonymous variants: 448 observed, 413.45 expected, observed/expected ratio (o/e) 1.08, 90% interval 1 to 1.17.
Homologues: Orthologues: chimpanzee PCDHB10 (94% identical), macaque PCDHB10 (92% identical), rat AC131360.1 (77% identical), mouse Pcdhb18 (76% identical). Paralogues in human: PCDHB9 (90% identical), PCDHB7 (75% identical), PCDHB3 (74% identical), PCDHB14 (74% identical), PCDHB2 (74% identical), PCDHB15 (73% identical), PCDHB11 (73% identical), PCDHB13 (73% identical), PCDHB8 (73% identical), PCDHB4 (72% identical), PCDHB12 (72% identical), PCDHB5 (72% identical), and 49 more.
Diseases named in the same sentence as PCDHB10 in open-access papers:
PCDHB10 is named in the same sentence as 11 diseases in open-access papers, as found by Europe PMC text mining. Sharing a sentence is not in itself a finding about the gene and the disease. The quoted sentences say what the papers report.
Anxiety (1 paper, 2019). Intense feelings of nervousness, tension, or panic often arise in response to interpersonal stresses. "Common variants in MTR, PPARA, ABCC3, CALML5, CACNB2 and PCDHB10 genes were associated with deficits in neurocognitive tests performance, whereas a variant in SLCO1B1 and EPHA5 genes was associated with anxiety and depression." (PMID 31181069, 2019). "Functionally predicted germline common variants in MTR, PPARA, SLCO1B1, ABCC3, CALML5, CACNB2 and PCDHB10 genes were found to be significantly associated with deficits in neurocognitive tests performance, whereas a variant in EPHA5 gene was significantly associated with both anxiety and depression." (PMID 31181069, 2019).
dementia (1 paper, 2024). Loss of intellectual abilities interfering with an individual's social and occupational functions. "Other correlations within the top 10 most significant include PLEKHH3, RGS14, LRCH1, and PCDHB10, notable for their prior implication in dementia and aging." (PMID 38469573, 2024).
diabetes (1 paper, 2022). "There were 8 differentially methylated genes (CDH2/PCDHB10/PCDHB11/PCDHB14/PCDHB16/PCDHB3/PCDHB6/PCDHB9) in the LAA subgroup and 1 (CDH2) in the SVD subgroup after adjusting for smoking, drinking, history of hypertension and diabetes, and blood lipid levels (p < 0.05)." (PMID 35480311, 2022).
glioblastoma (1 paper, 2023). The most malignant astrocytic tumor (WHO grade IV). "Interestingly, it has also been shown to be upregulated in glioblastoma, suggesting PCDHB10 may associate with different proteins, depending on cell type to exert its action." (PMID 37873862, 2023).
ovarian carcinoma (1 paper, 2023). A malignant neoplasm originating from the surface ovarian epithelium. "Of paramount significance, we identify three promising ovarian cancer targets suitable for ADC development: LRP6, PCDHB10, and PCDHB15." (PMID 37873862, 2023).
cancer (2 papers, 2015 to 2024). A tumor composed of atypical neoplastic, often pleomorphic cells that invade other tissues. "The HLM score was constructed based on six genes, AGXT, TRIB2, ELFN2, PCDHB10, CALCA, and CD79A, which have been previously reported to be associated with the tumorigenesis and progression of various cancer types, including CRC, as well as chemotherapy resistance." (PMID 38902737, 2024).
tumour (1 paper, 2023). "However, similar to PCDHB10, it has been reported as a tumour suppressor." (PMID 37873862, 2023). "GABRB1, PCDHB10, and LRP6 also showed that 80% to 90% of the patients exhibited expression of the biomarker in more than 75% of tumour cells." (PMID 37873862, 2023).
PCDHB10 also shares sentences with these, for which no sentence is quoted: depression (1 paper); Hypertension (1); hypothyroidism (1); neurological disease (1).